TRIM2 (tripartite motif containing 2)
Diseases named in the same sentence as TRIM2 in open-access papers (continued):
Sharing a sentence is not in itself a finding about the gene and the disease.
cancer (14 papers, 2016 to 2024). A tumor composed of atypical neoplastic, often pleomorphic cells that invade other tissues. "One example is the finding that TRIM2 is a target of non-coding microRNA-181c, which has been implicated in cancer signalling." (PMID 29958463, 2018). "High levels of TRIM2 were linked to a worse chance of spread of cancer to distant sites." (PMID 38893070, 2024). "This suggests that TRIM2 may be involved in the pathogenesis of cancer via different mechanisms, although the underlying mechanism may be complex and diverse, requiring further validation." (PMID 38893070, 2024). "Further validation through in vivo and in vitro analysis using BC models to investigate whether TRIM2 expression impacts cancer cell proliferation, invasion, and the underlying mechanisms of development and progression is warranted." (PMID 38893070, 2024). "TRIM2 overexpression significantly inhibited the migration, invasion, and proliferation of cancer cells." (PMID 36051486, 2022). "The analysis obtained from the starBase Pan-Cancer Analysis Platform proved a reduction of TRIM2 expression in ccRCC (n = 535) tissues compared to the normal (n = 72) tissues." (PMID 35342411, 2022). "After TRIM2 overexpression and treatment with the three different drugs, the survival rate of TRIM2-overexpressing cancer cells was significantly increased, while the survival rate of TRIM2 knockdown cancer cells was significantly reduced." (PMID 36051486, 2022). "In cancer studies, recent studies have shown that TRIM2 is highly expressed in many primary diseases such as breast cancer, liver cancer, and viral hepatitis." (PMID 32536816, 2020). "By affecting the ubiquitination levels of different substrate proteins, TRIM2 may play inconsistent cancer-promoting or cancer-inhibiting roles." (PMID 33714206, 2021). "Thus, whether TRIM2 mediates oxidative stress and leads to the production of a large amount of ROS in other cancers remains to be further studied." (PMID 36051486, 2022). "The Genomics of Drug Sensitivity in Cancer (GDSC) database was exploited to analyze the relationship between the drug sensitivity of ccRCC cell lines and the expression of TRIM2." (PMID 33223511, 2020). "TRIM2 is a diagnostically significant and conserved element of the SOX10 signature in BBC (breast basal-like carcinomas) cell lines." (PMID 27911271, 2017). "Other target genes, including Rho-associated, coiled-coil containing protein kinase 1 (ROCK1) and tripartite motif containing 2 (TRIM2), have also been identified as being controlled by miR-145 in cancer." (PMID 27412561, 2016). "This review focuses on TRIM2-related research and development in various fields, including both nonmalignant diseases and cancers." (PMID 36051486, 2022). "Notably, to date, there have been no TRIM2 inhibitors made commercially available for cancer therapy." (PMID 38893070, 2024). "Thus, dysregulated miRNA-target gene pairs involved in these genes like miR-21/GNE, miR-369/TRIM2, and miR-203a/PDE7A might promote the migration of cancer cells." (PMID 30627543, 2018). "Given that TRIM2 appears to have limited bearing on physiological ischemia-driven angiogenesis, TRIM2-directed therapies may represent safer alternatives to current anti-angiogenic strategies for the treatment of atherosclerotic CVD, cancer and chronic rheumatological conditions." (PMID 38542330, 2024).
infection (6 papers, 2017 to 2024). The state of being infected such as from the introduction of a foreign agent such as serum, vaccine, antigenic substance or organism. "We previously identified SIRPA as a host restriction factor when testing which members of the TRIM2 interactome also diminished NWA infection." (PMID 34097709, 2021). "ALA-synthase plays an important role in the production of heme TRIM2 E3 ubiquitin ligase induced during late erythropoiesis, which indicated a connection to hematological and iron (heme) regulation during infection." (PMID 33712587, 2021). "We also performed JUNV-C1, LCMV and VSV VIAs with SIRPA KO and WT BMDMs; cells from TRIM2 KO mice served as a control for the arenavirus infections." (PMID 34097709, 2021). "As we saw with the BMDMs from the mutant mice, the B construct had no antiviral activity against Candid 1, whereas both full-length mouse and human TRIM2 and the C constructs suppressed infection." (PMID 30726215, 2019). "SIRPA knockdown in the context of TRIM2 overexpression restored infection levels almost to that seen in control cells." (PMID 30726215, 2019). "TRIM2 overexpression resulted in decreased infection by Junín pseudoviruses as well as Candid 1, and as we showed previously, treatment with TRIM2 siRNA increased infection." (PMID 30726215, 2019). "In a small interfering RNA (siRNA) screen for host factors that play a role in Junín virus entry, we identified a number of host genes that alter infection, including tripartite motif 2 (TRIM2), which was antiviral." (PMID 30726215, 2019). "TRIM2, one of the proteins mutated in Charcot Marie Tooth Disease, blocks the entry of new world arenaviruses into cells, a novel mechanism for antiviral TRIM proteins, which generally restrict viruses at other stages of infection." (PMID 30726215, 2019). "In contrast, TRIM2 knockdown increased and overexpression decreased infection by Tacaribe virus." (PMID 30726215, 2019). "We also tested whether TRIM2 affected infection by the NWA Tacaribe virus and pseudoviruses bearing the GPs from the OWAs Lassa virus and LCMV." (PMID 30726215, 2019). "We then tested whether in vivo infection would be affected by TRIM2 deletion." (PMID 30726215, 2019). "Next, we tested whether infection with Candid 1 altered phosphorylation of TRIM2 or SIRPA." (PMID 30726215, 2019). "We found that SIRPA limited infection of EBOV GP, MACV GP and VSV G pseudoviruses while knockdown of TRIM2 only affected infection by MACV and of TIM-1 by EBOV pseudotypes." (PMID 34097709, 2021). "Here, using Trim2-knockout mice with different deletions, we show that TRIM2 functions in vivo to suppress NWA infection." (PMID 30726215, 2019). "SIRPA overexpression in U2OS cells blocked Candid 1 infection to a similar extent, as TRIM2 overexpression and SIRPA knockdown also increased infection by Parodi-GP pseudotyped MLV." (PMID 30726215, 2019). "Moreover, we show that a member of the TRIM2 interactome, signal regulatory protein α (SIRPA), which is well-known for inhibiting phagocytosis by macrophages, interacts with TRIM2 and also blocks NWA infection." (PMID 30726215, 2019). "We also showed that SIRPA phosphorylation is decreased upon infection; although TRIM2 also contains phosphotyrosines, infection did not lead to its dephosphorylation." (PMID 30726215, 2019). "Again, only TRIM2 and SIRPA depletion resulted in increased infection." (PMID 30726215, 2019). "Whether infection leads to SIRPA dephosphorylation and disassociation from TRIM2 or follows the dissociation is currently under investigation." (PMID 30726215, 2019). "Moreover, when we coimmunoprecipitated TRIM2 and SIRPA, we found that the interaction between TRIM2 and SIRPA decreased upon infection." (PMID 30726215, 2019). "Only JUNV-C1 and not LCMV showed higher infection of TRIM2 KO cells." (PMID 34097709, 2021).
infection (continued). "Taken together, these data suggest that phosphorylated SIRPA binds to TRIM2 and that this complex blocks virus internalization; dephosphorylation of SIRPA, either directly by SHP-2 or by other cellular phosphatases activated by infection, leads to dissociation of the complex and allows infection." (PMID 30726215, 2019). "SIRPA and TRIM2 also colocalized in transfected U2OS cells; this colocalization was not affected by NWA infection." (PMID 30726215, 2019). "However, knockdown of SIRPA in strain A or B mice did not further increase infection, nor was SIRPA surface expression diminished in the TRIM2 knockout mice." (PMID 30726215, 2019).
neurological diseases (3 papers, 2015 to 2025). "Changes in TRIM2 expression have long been related to human nervous system diseases, and TRIM2 plays an important role in the nervous system." (PMID 36051486, 2022). "In addition, TRIM2 plays a role in neuronal differentiation, axonal growth, and related nervous system diseases." (PMID 36051486, 2022).
neurodegenerative disease (1 paper, 2021). A disorder of the central nervous system characterized by gradual and progressive loss of neural tissue and neurologic function. "Tripartite Motif Containing 2 (TRIM2), a ubiquitin ligase that contributes to normal brain function, is dysregulated in AD and other neurodegenerative diseases and knockdown of TRIM2 in mice results in severe neurodegeneration." (PMID 34483928, 2021).
TRIM2 also shares sentences with these, for which no sentence is quoted: Tremor (3 papers); Charcot-Marie-Tooth disease (2); peripheral neuropathies (2); asthma (1); atherosclerosis (1); Autoimmunity (1); colon cancer (1); glioma (1); hepatocellular carcinoma (1); liver disease (1); malignant glioma (1); muscle atrophy (1); Onset (1); sarcopenia (1).